TRAPPC12 (trafficking protein particle complex subunit 12)
Description:
Component of the TRAPP complex, which is involved in endoplasmic reticulum to Golgi apparatus trafficking at a very early stage. Also plays a role in chromosome congression, kinetochore assembly and stability and controls the recruitment of CENPE to the kinetochores.
Synonyms: TTC-15; TTC15; CGI-87; PEBAS
Tractability: PROTAC: ubiquitination databases record sites on it; its protein half-life has been measured.
Gene: Protein-coding gene on chromosome 2 (3,379,674 to 3,485,094, forward strand). Ensembl gene ENSG00000171853.
Subcellular location: Endoplasmic reticulum-Golgi intermediate compartment; Nucleus
Subcellular location (Human Protein Atlas): Golgi apparatus; Nucleoplasm
Pathways (Reactome):
Vesicle-mediated transport: RAB GEFs exchange GTP for GDP on RABs
Gene Ontology:
Molecular function: protein binding
Biological process: endoplasmic reticulum to Golgi vesicle-mediated transport; Golgi organization; metaphase chromosome alignment; positive regulation of protein localization to kinetochore; regulation of kinetochore assembly; COPII vesicle coating
Cellular component: endoplasmic reticulum-Golgi intermediate compartment; Golgi apparatus; kinetochore; nucleoplasm; nucleus; perinuclear region of cytoplasm; TRAPP complex; cytoplasm; cytosol; TRAPPIII protein complex
Genetic constraint (gnomAD): Loss-of-function variants: 51 observed, 54.05 expected, observed/expected ratio (o/e) 0.94, 90% interval 0.75 to 1.19. The upper end of that interval is the gene's LOEUF score, 1.19, which puts it in group 5 of 6, group 1 being the genes least tolerant of losing a copy. Missense variants: 1,021 observed, 926.36 expected, observed/expected ratio (o/e) 1.1, 90% interval 1.05 to 1.16. Synonymous variants: 440 observed, 403.92 expected, observed/expected ratio (o/e) 1.09, 90% interval 1.01 to 1.18.
Homologues: Orthologues: chimpanzee TRAPPC12 (99% identical), macaque TRAPPC12 (84% identical), mouse Trappc12 (79% identical), rat Trappc12 (79% identical), dog TRAPPC12 (78% identical), pig TRAPPC12 (77% identical), guinea pig TRAPPC12 (76% identical), rabbit TRAPPC12 (71% identical), tropical clawed frog trappc12 (66% identical), zebrafish trappc12 (58% identical), Drosophila melanogaster CG11396 (23% identical), Caenorhabditis elegans trpp-12 (14% identical).
Diseases named in the same sentence as TRAPPC12 in open-access papers:
TRAPPC12 is named in the same sentence as 7 diseases in open-access papers, as found by Europe PMC text mining. Sharing a sentence is not in itself a finding about the gene and the disease. The quoted sentences say what the papers report.
cervical adenocarcinoma (1 paper, 2021). An adenocarcinoma arising from the cervical epithelium. "Fourth, in our study, after the evaluation of WES data in 20 cervical adenocarcinomas, six genes (i.e., PIK3CA, KRAS, TRAPPC12, NDN, GOLGA6L4, and BAIAP3) were predicted as driver genes that could promote tumor formation and development." (PMID 33398034, 2021).
ciliopathy (1 paper, 2020). A genetic disorder of the cellular cilia or the cilia anchoring structures, the basal bodies, or of ciliary function. "We found a ciliopathy protein, oral-facial-digital syndrome 1 (OFD1), interacting with the TRAPPIII-specific subunits TRAPPC8 and TRAPPC12." (PMID 32258032, 2020).
tumor (2 papers, 2021 to 2022). "In a subsample of patients whose tumours were profiled for RNA (n = 96), feature S(1,−1)SumAverg was significantly associated with the expression of gene MOV10L1, LRP1B, ZFY, PITX2, TRAPPC12, MMGT1 and PPP2R2C (all P < 0.05)." (PMID 36050449, 2022).
cancer (1 paper, 2020). A tumor composed of atypical neoplastic, often pleomorphic cells that invade other tissues. "It was reported that TRAPPC12 also localized to the ER exit sites and ERGIC in cancer cells." (PMID 32258032, 2020). "TRAPPC12 signal was present in large punctate structure mostly on ER exit sites and ERGIC, but poorly on Golgi apparatus, as the previous report in cancer cells." (PMID 32258032, 2020).
TRAPPC12 also shares sentences with these, for which no sentence is quoted: Lissencephaly (1 paper); Periventricular heterotopia (1); rhabdomyolysis (1).